MIR10B (microRNA 10b)
Synonyms: hsa-mir-10b; MIRN10B; miRNA10B; mir-10b
Gene: MicroRNA gene on chromosome 2 (176,150,303 to 176,150,412, forward strand). Ensembl gene ENSG00000207744.
Pathways (Reactome):
Cell-Cell communication: Regulation of CDH1 mRNA translation by microRNAs
Gene Ontology:
Biological process: miRNA-mediated post-transcriptional gene silencing
Cellular component: RISC complex
Homologues: Orthologues: chimpanzee ptr-mir-10b (100% identical), macaque mml-mir-10b (99% identical), rat Mir10b (95% identical), dog MIR10B (87% identical), pig MIR10B (87% identical), zebrafish mir10d (78% identical), tropical clawed frog xtr-mir-10b (73% identical), zebrafish mir10b-1 (62% identical), guinea pig MIR10B (60% identical), mouse Mir10b (59% identical), Drosophila melanogaster mir-10 (45% identical). Paralogues in human: MIR10A (65% identical), MIR125B2 (35% identical), MIR125A (32% identical), MIR125B1 (32% identical), MIR99A (32% identical), MIR99B (30% identical), MIR100 (29% identical).
Diseases named in the same sentence as MIR10B in open-access papers:
MIR10B is named in the same sentence as 5 diseases in open-access papers, as found by Europe PMC text mining. Sharing a sentence is not in itself a finding about the gene and the disease. The quoted sentences say what the papers report.
ankylosing spondylitis (1 paper, 2021). An autoimmune chronic inflammatory disorder characterized by inflammation in the vertebral joints of the spine and sacroiliac joints. "MIR10B has been shown to regulate Th17 cells in patients with ankylosing spondylitis but no studies have specifically associated it with RA." (PMID 33968050, 2021).
diffuse large B-cell lymphoma (1 paper, 2022). "Similarly, high MIR10B levels have been found in patients with diffuse large B-cell lymphoma and mammary tumors." (PMID 35765483, 2022).
lymphoid tumor (1 paper, 2022). "A total of six miRNA orthologs – MIR21, MIR30E, MIR106B, MIR10B, MIR200A, and MIR200B were identified as differentially expressed orthologs among mammary tumor cell lines, lymphoid tumor cell lines, and normal epithelial cell cultures (importance ≥10 and p≤0.01) (Figure-2)." (PMID 35765483, 2022).
tumor (2 papers, 2020 to 2022). "Another striking difference between parental and MIR10B−/− cells was a reduced capacity to grow out of tumor spheroids upon transfer to culture dishes." (PMID 32276641, 2020). "Only MIR10B, MIR21, and MIR30E inherited RP scores of <10 and were thus chosen as candidate orthologs for further tumor classification analysis using the SVM model." (PMID 35765483, 2022).
MIR10B also shares sentences with these, for which no sentence is quoted: mammary tumor (1 paper).